BLTP2 (bridge-like lipid transfer protein family member 2)
Description:
Tube-forming lipid transport protein which binds to phosphatidylinositols and affects phosphatidylinositol-4,5-bisphosphate (PtdIns-4,5-P2) distribution.
Synonyms: BCOX1; KIAA0100; DKFZp686M0843; MGC111488; CT101; BCOX; FMP27; Hob
Tractability: Antibody: UniProt places it where antibodies can reach, with medium confidence; UniProt predicts a signal peptide or a membrane-spanning region; its Gene Ontology location is reachable by antibodies, with medium confidence. PROTAC: ubiquitination databases record sites on it.
Gene: Protein-coding gene on chromosome 17 (28,614,440 to 28,645,454, reverse strand). Ensembl gene ENSG00000007202.
Subcellular location: Cell membrane; Endoplasmic reticulum membrane; Mitochondrion membrane
Subcellular location (Human Protein Atlas): Cytosol; Nuclear speckles
Gene Ontology:
Molecular function: phosphatidylinositol binding
Cellular component: endoplasmic reticulum membrane; endoplasmic reticulum-plasma membrane contact site; mitochondrial membrane; plasma membrane
Genetic constraint (gnomAD): Loss-of-function variants: 126 observed, 260.69 expected, observed/expected ratio (o/e) 0.48, 90% interval 0.42 to 0.56. The upper end of that interval is the gene's LOEUF score, 0.56, which puts it in group 2 of 6, group 1 being the genes least tolerant of losing a copy. Missense variants: 2,300 observed, 2,819.9 expected, observed/expected ratio (o/e) 0.82, 90% interval 0.79 to 0.84. Synonymous variants: 1,053 observed, 1,067.2 expected, observed/expected ratio (o/e) 0.99, 90% interval 0.94 to 1.04.
Homologues: Orthologues: chimpanzee KIAA0100 (99% identical), macaque KIAA0100 (99% identical), guinea pig BLTP2 (95% identical), dog BLTP2 (95% identical), pig BLTP2 (95% identical), mouse Bltp2 (94% identical), rat Rskr (94% identical), rabbit BLTP2 (93% identical), tropical clawed frog bltp2 (71% identical), zebrafish BLTP2 (65% identical), Drosophila melanogaster hob (32% identical), Caenorhabditis elegans bltp-2 (27% identical).
Diseases named in the same sentence as BLTP2 in open-access papers:
BLTP2 is named in the same sentence as 21 diseases in open-access papers, as found by Europe PMC text mining. Sharing a sentence is not in itself a finding about the gene and the disease. The quoted sentences say what the papers report.
breast carcinoma (6 papers, 2014 to 2025). "Why BLTP2 is particularly important for the proliferation of several breast cancer cell lines and the aggressiveness of MDA-MB-231 is an open question." (PMID 40579455, 2025). "We observed that the median survival score of BLTP2 deletion mutants is lower than deletion mutants of the other genes, suggesting that BLTP2 supports the growth of many invasive breast cancer cell lines." (PMID 40579455, 2025). "Whether BLTP2 controls tumorigenesis in a PE and PM fluidity-dependent manner and whether BLTP2 is a targetable protein in aggressive breast cancer treatment will be determined in future studies." (PMID 40579455, 2025). "BLTP2 also facilitates breast cancer cell growth, suggesting a separate role in tumorigenesis." (PMID 40579455, 2025). "BLTP2 expression correlates with breast cancer aggressiveness." (PMID 40579455, 2025). "To investigate the importance of BLTP2 in cancer, we examined data from the Cancer Dependency Map (DepMap) and found that BLTP2 is highly expressed and required for optimal grown of many invasive breast cancer cell lines, suggesting a critical role in breast cancer progression." (PMID 40579455, 2025). "BLTP2 has also been suggested to modulate the aggressiveness of both basal-like and non-basal-like breast cancer cells." (PMID 40579455, 2025). "Alternatively, BLTP2 could affect some other aspect of phospholipid homeostasis in MDA-MB-231 and some other breast cancer cell lines." (PMID 40579455, 2025).
triple-negative breast carcinoma (3 papers, 2014 to 2025). An invasive breast carcinoma which is negative for expression of estrogen receptor (ER), progesterone receptor (PR), and human epidermal growth factor receptor 2 (HER2). "We also find that BLTP2 sustains proliferation of the triple negative breast cancer (TNBC) cell line MDA-MB-231 in a zebrafish xenograft model, indicating it is pro-tumoural." (PMID 40579455, 2025). "We found that BLTP2 facilitates growth of a triple negative breast cancer cell line and sustains its aggressiveness in an in vivo model of metastasis, suggesting maintenance of PM fluidity by BLTP2 may be critical for tumorigenesis in humans." (PMID 40579455, 2025).
cervical cancer (1 paper, 2025). A primary or metastatic malignant neoplasm involving the cervix. "We found that CRISPR–Cas9-mediated knock-out of BLTP2 (BLTP2-KO) in the cervical cancer cell line HeLa also reduced its rate of proliferation." (PMID 40579455, 2025).
invasive breast carcinoma (1 paper, 2025). A carcinoma that infiltrates the breast parenchyma. "We assessed the role of BLTP2 in the survival of 46 invasive breast cancer cell lines from data available in DepMap." (PMID 40579455, 2025).
cancer (4 papers, 2014 to 2025). A tumor composed of atypical neoplastic, often pleomorphic cells that invade other tissues. "Our results suggest BLTP2 is pro-tumoural and regulates invasiveness, presumably by controlling the PM fluidity of some cancer cells." (PMID 40579455, 2025). "Together, these results suggest that BLTP2 is important for cell growth in human cells and may be particularly important for rapid proliferation of some cancer cells." (PMID 40579455, 2025).
BLTP2 also shares sentences with these, for which no sentence is quoted: tumor (9 papers); breast tumor (2); acute monocytic leukaemia (1); acute monocytic leukemia (1); adrenocortical carcinoma (1); Ductal Carcinomas (1); ductal in situ carcinoma (1); epidermoid carcinoma (1); glioblastoma (1); infection (1); invasive ductal carcinomas (1); lung (1); lymph node metastasis (1); osteosarcoma (1); ovarian carcinoma (1); prostate carcinoma (1).